PMP22 (peripheral myelin protein 22)
Diseases named in the same sentence as PMP22 in open-access papers (continued):
Sharing a sentence is not in itself a finding about the gene and the disease.
Charcot-Marie-Tooth disease type 1A (31 papers, 2005 to 2026). "For instance, duplications of the PMP22 gene are known to cause Charcot-Marie-Tooth type 1A disease by increasing gene dosage, leading to peripheral nerve dysfunction." (PMID 41384039, 2025). "Charcot-Marie-Tooth disease type 1A (CMT1A) is a hereditary demyelinating neuropathy that is caused by a duplication of the PMP22 gene located on chromosome 17." (PMID 40026692, 2025). "Charcot-Marie-Tooth disease type 1A (CMT1A) is a hereditary neuropathy caused by the duplication of the PMP22 gene, leading to Schwann cell dysfunction and peripheral demyelination." (PMID 40666492, 2025). "Pmp22 is a dosage sensitive gene which causes hereditary neuropathy with liability to pressure palsies in haplo-insufficiency and Charcot-Marie-Tooth disease type 1A when overexpressed." (PMID 38383802, 2024). "Duplications of PMP22 are associated with Charcot-Marie-Tooth disease type 1A, whereas deletions cause distal hereditary motor neuronopathy type VIIB." (PMID 36781956, 2023). "The first group is caused by a PMP22 duplication, and constitutes the majority of Charcot-Marie-Tooth disease type 1A (CMT1A)." (PMID 24646194, 2014). "A Czech patient had a phenotype caused by the combination of a point mutation in the DMD gene and a duplication of the PMP22 gene causing CMT1A (Charcot-Marie-Tooth disease type 1A), and a Chinese patient had a phenotype caused by a duplication of the PMP22 gene and a DMD deletion." (PMID 37569734, 2023). "Duplication causes Charcot-Marie-Tooth disease type 1A (CMT1A) by overexpressing PMP22, resulting in abnormal myelin formation, chronic demyelination, and progressive distal weakness." (PMID 41179108, 2025). "Conversely, duplication of PMP22 causes Charcot-Marie-Tooth disease type 1A (CMT1A), characterized by hypomyelination of medium to large caliber axons." (PMID 38383802, 2024). "Charcot-Marie-Tooth disease type 1A (CMT1A), the most common inherited demyelinating peripheral neuropathy, is caused by PMP22 gene duplication." (PMID 35579942, 2022). "miR-4731 is located at chr17p12 (chr17:15,154,944-15,155,013) in an intron (>5 kb from intron-exon border) of the peripheral myelin protein 22 gene (PMP22), which is commonly associated with hereditary Charcot-Marie-Tooth disease type 1A (CMT1A)." (PMID 27331623, 2016). "In particular, elevated expression of PMP22 causes Charcot-Marie-Tooth disease type 1A (CMT1A), an autosomal dominant condition that is characterized by progressive motor and sensory polyneuropathy." (PMID 21518455, 2011). "The first form results from a duplication of the PMP22 gene giving rise to Charcot-Marie-Tooth disease type 1A (CMT1A)." (PMID 38667620, 2024). "Charcot-Marie-Tooth disease type 1A (CMT1A) is the most common inherited motor and sensory neuropathy, and is caused by duplication of PMP22, alterations of which are a characteristic feature of demyelination." (PMID 30110925, 2018). "Duplication of PMP22 at 17p12 causes Charcot-Marie-Tooth disease type 1A (CMT1A)." (PMID 29329513, 2018). "It is also a homologue of Pmp22, which is involved in Charcot Marie Tooth disease type 1A, a sensory neuropathy common in some forms of ataxia." (PMID 23028291, 2012). "Charcot-Marie-Tooth disease type 1A (CMT1A), caused by duplication of the peripheral myelin protein 22 (PMP22) gene, and CMT1B, caused by mutations in myelin protein zero (MPZ) gene, are the two most common forms of demyelinating CMT (CMT1), and no treatments are available for either." (PMID 35501630, 2022). "In inherited neuropathies like Charcot-Marie-Tooth disease type 1A (CMT1A), duplication of the PMP22 gene results in Schwann cell dysfunction and impaired axonal support." (PMID 40506883, 2025). "Variation in gene dosage of Pmp22 can lead to Charcot-Marie-Tooth disease type 1A (CMT1A) or Hereditary Neuropathy with Liability to Pressure Palsy (HNPP), two inherited motor/sensory neuropathies." (PMID 38123724, 2024).
Charcot-Marie-Tooth disease type 1A (continued). "Charcot-Marie-Tooth disease type 1A (CMT1A) is a common heritable form of the condition that develops when nerves in the body’s extremities, such as the hands, feet and arms, are damaged due to an extra copy of PMP22 gene being incorrectly produced." (PMID 38017287, 2023). "Copy number variation (CNV) may lead to pathological traits, and Charcot-Marie-Tooth disease type 1A (CMT1A), the commonest inherited peripheral neuropathy, is due to a genomic duplication encompassing the dosage-sensitive PMP22 gene." (PMID 37337674, 2023).
breast carcinoma (19 papers, 2010 to 2025). "PMP22 is expressed primarily in neural crest derived cell lineages (including melanocytes), however expression of PMP22 has also been associated with cell proliferation and survival in breast cancer." (PMID 27331623, 2016). "In this study we show that breast cancer patients with higher than median PMP22 gene expression had a 3.47 times higher risk to die of cancer than patients with lower than median PMP22 expression." (PMID 21159173, 2010). "PMP22 is a messenger RNA that has been associated with breast cancer and metastasis." (PMID 27021602, 2016). "In our study, knockout of Stk11 in murine breast cancer cell lines resulted in significant enrichment of cytoskeleton-related gene (Bpifb4), and cell adhesion/migration-related genes (Cdh5, Plat, and Pmp22), along with enhanced tumorigenicity in vivo." (PMID 41051525, 2025). "CNOT7 and its paralog CNOT8 can influence the stability of cell cycle-related genes MSMB, PMP22, and Cyclin G2 through their deadenylation ability, promoting cell proliferation in breast cancer." (PMID 41249119, 2025). "A case in point is G3BP1’s degradation of peripheral myelin protein 22 (PMP22) mRNA to inhibit the expression of PMP22, which can promote the proliferation of breast cancer cell." (PMID 37179344, 2023). "An earlier study compared the invasiveness and noninvasiveness of human breast cancer cell lines with normal breast epithelial cells and found that the PMP22 mRNA level increased." (PMID 36217151, 2022). "Here, we show that PMP22 depletion results in increased proliferation in breast cancer cells, which supports the role of PMP22 as a growth arrest-specific gene." (PMID 24321297, 2013). "This indicates a novel role for G3BP1 in the regulation of cell proliferation in breast cancer cells, perhaps via a regulatory effect on PMP22 expression." (PMID 24321297, 2013). "In this study we identified PMP22 mRNA levels as being influenced by G3BP1 in breast cancer cell lines." (PMID 24321297, 2013). "It is very interesting to further investigate the possible functions of PMP22 in breast cancer and to clarify its roles in tumor invasion, so that we can better understand its prognostic impact." (PMID 21159173, 2010). "PMP22 gene expression is a novel independent prognostic factor for disease-free survival and overall survival for breast cancer patients." (PMID 21159173, 2010). "Using cross validation, we compared the ranges of 5-year survival rates of breast cancer patients between models including and excluding PMP22 gene expression." (PMID 21159173, 2010). "The analysis of the proportion of explained variation suggests that gene expression of PMP22, ER status and pN variables are equally important to predict mortality of breast cancer." (PMID 21159173, 2010). "This is true for both DFS and OS, showing that PMP22 has an additive value in predicting survival after the diagnosis of breast cancer." (PMID 21159173, 2010). "Taking together, PMP22 gene expression is an independent prognostic factor for disease-free and overall survival for breast cancer patients." (PMID 21159173, 2010). "The analysis of PMP22 gene expression in breast cancer is also very complicated." (PMID 36217151, 2022). "However, G3BP1 inhibits the expression of peripheral myelin protein 22 (PMP22) mRNA, which plays a role in the regulation of breast cancer cell proliferation." (PMID 34526993, 2021). "KYNU, CTSD and PMP22 are known to be up‐regulated in advanced metastatic cancers and correlate with poor prognosis whereas LAMB1 encodes a laminin‐1 protein shown to have reduced expression in breast cancer." (PMID 25241147, 2015). "In this study, we did not only show that PMP22 gene expression has prognostic value on DFS and OS, we also showed that PMP22 gene expression is as powerful as nodal status and ER status to predict mortality of breast cancer patients by calculating the proportion of explained variation." (PMID 21159173, 2010).
breast carcinoma (continued). "Functional studies on PMP22 in breast cancer should be investigated to elucidate its roles in the progression of breast cancer and to explain if it could be a therapy target." (PMID 21159173, 2010). "In breast cancer, G3BP1 supported cell proliferation via increasing PMP22 expression." (PMID 35568705, 2022). "Since then, increased PMP22 expression has also been noted in invasive versus non-invasive mammary carcinoma cell lines, in (pre)malignant lesions versus normal pancreatic tissue, and in proliferative versus secretory phase endometrium." (PMID 22292074, 2012).
demyelinating peripheral neuropathy (13 papers, 2013 to 2026). "Charcot-Marie-Tooth (CMT) type 1A, the most common inherited demyelinating peripheral neuropathy, is caused by PMP22 gene duplication, leading to overproduction of PMP22 protein in Schwann cells." (PMID 41948127, 2026). "Charcot–Marie-Tooth type 1A (CMT1A) is the most common inherited demyelinating peripheral neuropathy caused by duplication of the peripheral myelin protein 22 (PMP22) gene." (PMID 41234933, 2025). "Although mutations and loss of functions of PMP22 are related to demyelinating peripheral neuropathies, PMP22 is also reported to increase the aggressiveness of various types of cancers." (PMID 31652725, 2019). "Duplication of PLP1 is a frequent cause of PMD33, 34, 35 and a similar gene dosage effect of PMP22 is responsible for the demyelinating peripheral neuropathy in Charcot-Marie-Tooth disease type 1A36." (PMID 24989451, 2014). "Charcot–Marie–Tooth disease type 1A (CMT1A) hereditary demyelinating peripheral neuropathies are linked with duplication or point mutations in the peripheral myelin protein 22 (PMP22) gene." (PMID 24175617, 2013). "Altered expression of peripheral myelin protein 22 (PMP22) results in demyelinating peripheral neuropathy." (PMID 38378628, 2024). "Several lines of transgenic mice and rats with multiple copies of the mouse Pmp22 or human PMP22 gene develop a peripheral demyelinating neuropathy, the severity of which is proportional to transgene copy number." (PMID 37337674, 2023). "For both patients carrying the PMP22 p.Q86X mutation, the NCS revealed a severe demyelinating polyneuropathy with a single digit ulnar motor nerve conduction velocity." (PMID 29127354, 2017). "The frequency of PMP22 duplications among the demyelinating polyneuropathy patients in this material was lower than average (18.7%), whereas the frequency of MPZ mutations (6.0%) and GJB1 mutations (6.7%) were close to average." (PMID 24053775, 2013). "Finally, mutations in SOX10 target genes including those encoding peripheral myelin protein 22 (PMP22), myelin protein zero (MPZ), and gap junction beta 1 (GJB1) cause demyelinating peripheral neuropathy." (PMID 27821050, 2016).
osteosarcoma (10 papers, 2010 to 2023). A usually aggressive malignant bone-forming mesenchymal neoplasm, predominantly affecting adolescents and young adults. "The gene list includes COPS3 in 17p11.2 and PMP22 in 17p12, which we and others previously suggested to act as causative oncogenes in osteosarcoma tumourigenesis." (PMID 22292074, 2012). "Taken together, these data suggest that, contrary to its original proposed property as being associated with cell growth arrest, PMP22 has an important proliferation-associated and oncogenic role, not only in osteosarcoma tumourigenesis, but in the development of other tumour types as well." (PMID 22292074, 2012). "In the proliferation experiment with highly metastatic osteosarcoma cell lines, the proliferation ability of osteosarcoma cells successfully transfected with PMP22 was significantly higher than controls." (PMID 36217151, 2022). "When an immortalized cell line of this type (iMSC#3) was induced to osteogenic differentiation, PMP22 expression increased to a level higher than was observed in any of the osteosarcoma lines, suggesting a role in osteoblast differentiation." (PMID 26672768, 2016). "We and others have previously reported upregulation of PMP22 expression in osteosarcoma tumours and cell lines." (PMID 22292074, 2012). "In an earlier small-scale study, we found genes COPS3 in 17p11.2 and PMP22 in 17p12 to be most consistently overexpressed after amplification in osteosarcomas, making these genes candidate oncogenes in that segment." (PMID 22292074, 2012). "We conclude that these genes, including COPS3 and PMP22, are candidate oncogenes in 17p11.2–p12 of importance in osteosarcoma tumourigenesis." (PMID 22292074, 2012). "Increased PMP22 expression was found in other pre-malignant or malignant tissues, like pancreatic tissues, osteosarcoma, and glioblastoma tissues." (PMID 21159173, 2010). "In osteosarcoma cells, PMP22 was proved to suppress cell proliferation, and Western blot results showed that the phosphorylation level of p38 was up-regulated by enhanced PMP22 expression." (PMID 30460078, 2017). "However, in osteosarcoma cells, PMP22 was proved to suppress cell proliferation by up-regulating the phosphorylation level of p38." (PMID 30460078, 2017). "Of note, overexpression of genes belonging to the amplified region (COPS3, PMP22, GID4, ARGHAP44, TOP3A, SHMT1, and RASD1) was studied in osteosarcoma cell lines." (PMID 35920001, 2022). "Summarizing the findings in the two sample sets (49 samples investigated at RNA and 25 samples at DNA level), PMP22-ELOVL5 occurred at a frequency of 9 % (7 of 74) and is the first recurrent fusion transcript reported in osteosarcoma." (PMID 26672768, 2016). "Based on our statistical analysis of the correlation between copy number increase and expression level for each of the top ranking genes, we identified RICH2, c17orf45, TOP3A, COPS3, SHMT1, PRPSAP2, PMP22, and RASD1 as candidate osteosarcoma oncogenes in the 17p11.2-p12 region." (PMID 22292074, 2012). "However, prognostic studies for the other candidate genes require the development of new antibodies (C17orf39, RICH2, RASD1) or testing of available antibodies on osteosarcoma tissues (TOP3A, COPS3, SHMT1, PRPSAP2, PMP22), which is presently underway." (PMID 22292074, 2012).
polyneuropathy (9 papers, 2010 to 2026). A disease or disorder affecting more than one nerve. "HNPP is another polyneuropathy caused by mutations in PMP22 and it is found to be inherited as an autosomal dominant trait." (PMID 41595476, 2026). "In contrast to CMT1, in which overexpression causes a gain-of function phenotype, this polyneuropathy leads to a loss-of function phenotype, underlining the normal physiological functions of PMP22." (PMID 41595476, 2026). "In addition, the p.I104FfsX7 mutation linked to an infantile-onset severe polyneuropathy led to a truncated PMP22 with a very low expression level, insoluble cytoplasmic aggregate formations, and the failure of cell membrane localization." (PMID 29127354, 2017). "Patients showing demyelinating or mixed polyneuropathy/intermediate nerve conduction velocities, and those in whom the polyneuropathy type is uncertain, should be tested with PMP22 MLPA and DNA sequencing of the MPZ and GJB1 genes." (PMID 24053775, 2013). "Genetic testing was performed according to polyneuropathy type; demyelinating/mixed: PMP22 duplication, MPZ, EGR2, LITAF, NEFL, PMP22, GJB1, axonal: MFN2, MPZ, NEFL, and GJB1." (PMID 24053775, 2013). "Three patients with polyneuropathy suspected to be genetic in origin, but not harboring PMP22 gene deletion/duplication, were offered WES." (PMID 32022442, 2020). "Further molecular genetic testing at age 9 for polyneuropathy, FSHD (facioscapulohumeral muscular dystrophy), and LGMD (limb-girdle muscular dystrophy) was negative (targeted testing of the CAPN3, FKRP and PMP22 genes was performed)." (PMID 36361862, 2022).
Ataxia (8 papers, 2012 to 2024). Ataxia refers to impaired coordination of voluntary muscle movement. "Because the peripheral aspects of the eighth nerve myelination are conferred by Schwann cells, and PMP22 is a principal functional constituent of compact myelin, we considered the likelihood that the ataxia and hearing loss might emanate from the inner ear." (PMID 38378628, 2024). "In particular, the frequency of the cerebellar ataxia was high in patients with NEFL mutations (72.7%), compared to GJB1 mutations (9.1%), PMP22 duplication (0%), and MFN2 mutations (0%)." (PMID 34768465, 2021). "As the clinical picture of visual loss resembled that of Leber hereditary optic neuropathy (LHON) presentation, and the neurological involvement suggested spinocerebellar ataxia, genetic testing for LHON and PMP22 was performed, which did not identify any pathogenic variant." (PMID 33938912, 2021). "In addition, cerebellar ataxia, which is commonly manifested in patients with NEFL mutations, is not well observed in the other genetic mutations, such as PMP22 and MFN2, except in 1 out of 11 patients with GJB1 mutations." (PMID 34768465, 2021). "In South Africa, limited genetic testing is available for non-muscle NMD and includes only PMP22 multiplex ligation-dependent probe amplification (MLPA) for GN and spinocerebellar ataxias 1, 2, 3, 6, 7, 12, 17 and Frataxin expansion screening for spastic ataxias." (PMID 37712079, 2023).
Sensory neuropathy (7 papers, 2012 to 2024). Peripheral neuropathy affecting the sensory nerves. "Subsequently, on account of this patient’s emerging motor/sensory neuropathy symptoms, a multiplex ligation-dependent probe amplification (MLPA) analysis of the PMP22 gene was performed." (PMID 38891946, 2024).